CXCL10 (C-X-C motif chemokine ligand 10)
Diseases named in the same sentence as CXCL10 in open-access papers (continued):
Sharing a sentence is not in itself a finding about the gene and the disease.
Stroke (continued). "In a multivariate analysis adjusted for age, atrial fibrillation, pre-stroke dependency, NIHSS on admission and right-sided lesion, CXCL10 and CXCL8 still remained independent predictors of death." (PMID 38861234, 2025). "Post‐stroke BHB therapy resulted in a substantial decrease in the expression of proinflammatory chemokines (CCL3, CXCL1, CXCL9, CXCL10), complement (C5/5a), cytokines (IFN‐γ), and myeloid cell activators (G‐CSF) in the ischemic hemisphere." (PMID 38666466, 2024). "Astrocytes promote microglial activation through the production of C-X-C motif chemokine ligand 10 (CXCL10), lipocalin-2 (Lcn2), and complement 3 (C3), as seen in models of stroke and epilepsy." (PMID 37274195, 2023). "However, the function of the CXCR3/CXCL10 axis in stroke remains unclear." (PMID 35912857, 2022). "CXCR3, the receptor of CXCL10, is known to reduce brain infarction and attenuate BBB disruption in stroke." (PMID 35091962, 2022). "In the ischemic penumbra, outside of the stroke core, microglia had reduced process ramification, reduced P2RY12 and TMEM119 protein expression, and less frequent or reduced CXCL10 expression." (PMID 32573436, 2020). "At day 22, most of the measured cytokines were slightly (CINC-1, CINC-2α/β, CINC-3, GM-CSF and VEGF) or markedly (CD54, CD62L, CXCL7, CXCL9, CXCL10, CCL3, CCL5, CCL20) induced by stroke compared to Ctl." (PMID 33204331, 2020). "sVCAM1, MMP-1, sRAGE, CXCL10 are higher in TBM patients with stroke compared with those without stroke, and other forms of meningitis in children." (PMID 38264653, 2023). "Pan-reactive astrocyte genes (Cxcl10 and Osmr), A1 neurotoxic genes (Amigo2, Ugt1a, Gpc4, H2-D1, and Iigp1), and A2 neuroprotective genes (Ptx3, Thbs2, and Tm4sf1) were all upregulated by NPD1 + RvD1 in the ipsilesional penumbra at 24 h after stroke." (PMID 37270727, 2023). "In the present population-based sample, but not in post-stroke patients, the proinflammatory cytokine interferon gamma-induced protein (IP-10), also known as CXCL10, was significantly increased in subjects with fatigue compared to the non-fatigue group." (PMID 36756348, 2022). "dBET1 markedly reduced inflammation and oxidative stress after stroke, indicated by multiple pro-inflammatory cytokines and chemokines including IL-1β, IL-6, TNF-α, CCL2, CXCL1 and CXCL10, and oxidative damage markers 4-hydroxynonenal (4-HNE) and gp91phox and antioxidative proteins SOD2 and GPx1." (PMID 35761277, 2022). "CXCL10 was also expressed by astrocytes, but only weakly by microglia and not by neurons after stroke." (PMID 35912857, 2022). "Cxcr3 KO in CD8+ TRLs or the absence of CXCL10 in the stroke lesions impairs brain infiltration by CD8+ TRLs and hinders their neuroprotective properties." (PMID 35912857, 2022). "In another study, the concentrations of lipocalin-2, soluble receptor for advanced glycation end products (sRAGE) and CXCL10 were significantly higher in the CSF of children with TBM-related stroke compared to TBM without stroke." (PMID 35095865, 2021). "Although LIF treatment prevented the increase in splenic CXCL10 in young male rats, we did not observe a significant change in splenic CXCL10 levels after a stroke or LIF treatment among aged rats of either sex." (PMID 33376583, 2020). "ELISAs confirmed the upregulation of CXCL10 in brain lysates, but not in blood, 1 day after stroke." (PMID 35912857, 2022). "CXCL-10 was not predictive of stroke severity based on mRS score in our study." (PMID 31312177, 2019). "In order to explore the roles of astrocytes in post-stroke inflammation, the levels of inflammatory factors were detected in primary astrocytes at 0 h, 6 h, 12 h, 24 h, and 48 h after 6-h OGD, including TNF-α, IL-6, IL-10, inducible nitric oxide synthase (iNOS), IL-1β, and CXCL10." (PMID 31426811, 2019).
Stroke (continued). "In the same vein, JAK3 inhibition with 10 mg/kg decernotinib did not affect stroke-induced upregulation of Ccl2, Cxcl10, and Cxcl1, chemokines important for immune cell trafficking, nor proinflammatory mediators IL-1β, IL-6, Tnfα, Ptgs2, and Mmp-9 that exacerbate stroke damage." (PMID 28790974, 2017). "Supporting the brain-homing properties of CXCR3/CXCL10 for CD8+ TRLs after stroke, CD8+ TRLs failed to infiltrate ischemic brain in Cxcl10-KO and Cxcr3-KO mice." (PMID 35912857, 2022). "Immunostaining demonstrated the expression of CXCL10 protein, but not CXCL9 or CXCL11, along CD31+ vessels in the ischemic brain 1 day after stroke." (PMID 35912857, 2022).
cerebral malaria (43 papers, 2007 to 2025). A sequestration of Plasmodium falciparum in the brain, which can cause coma and/or seizures. "Both CXCL9 and CXCL10 play important roles in the inflammation that drives cerebral malaria-associated neuropathology, namely in terms of T cell adhesion to endothelial cells, and recruitment to the brain parenchyma." (PMID 35787830, 2022). "The chemokine CXCL10 is associated with pathogenesis of cerebral malaria in Plasmodium falciparum infection." (PMID 34381047, 2021). "Concerning the CSF, increases of CXCL10 have been demonstrated in other CNS infections, such as encephalitis caused by viruses and cerebral malaria." (PMID 28821016, 2017). "falciparum infection, IP-10/CXCL10 has been identified as biomarker (in serum and cerebrospinal fluid) associated with elevated risk of fatal cerebral malaria." (PMID 28118834, 2017). "Stratification analysis of female gender on association between CXCL10 promoter polymorphisms (−135G>A and −1447A>G) and cerebral malaria." (PMID 24349056, 2013). "Stratification analysis of male gender on association between CXCL10 promoter polymorphisms (−135G>A and −1447A>G) and cerebral malaria." (PMID 24349056, 2013). "Genotype and allele frequency of CXCL10 polymorphisms in patients with cerebral malaria and non-cerebral malaria." (PMID 24349056, 2013). "Increased expression of CXCL10 above basal levels has been linked to fatal cerebral malaria." (PMID 33424841, 2020). "Furthermore, polymorphisms in the human CXCL10 gene that affect plasma CXCL10 correlate with the incidence of cerebral malaria, particularly in males, in a manner consistent with the data from the experimental studies in mice." (PMID 25177551, 2014). "A study of CXCL10 wildtype (WT) and Knockout (KO) mice showed efficient parasite control in KO mice while WT mice progressed to cerebral malaria." (PMID 37465667, 2023). "The significance of these findings is bolstered by previous work showing pharmacological reduction of CXCL10 in addition to anti-malarial treatment leading to increased survival of mice in an in vivo cerebral malaria model." (PMID 36618355, 2022). "We also note that co-administration of EV-loaded miR-451a and let-7i-5p led to the significant reduction of the TLR4 dependent release CXCL10, a biomarker of cerebral malaria severity." (PMID 36618355, 2022). "During cerebral malaria, the monocyte-derived dendritic cells (MO-DCs) produce CXCL10 and CXCL9, but it is still unclear which APCs are responsible for producing CXCR3 ligands during T. cruzi infection." (PMID 32574175, 2020). "The genetic deletion of CXCL-10 (CXCL-10-/-) or of its receptor CXCR3 (CXCR3-/-) in experimental cerebral malaria (ECM) studies involving Plasmodium berghei ANKA infections attenuates ECM pathogenesis and mortality." (PMID 31844087, 2019). "Recent studies indicate that interferon gamma inducible chemokine, CXCL10, is a strong predictor of both human and experimental cerebral malaria." (PMID 24349056, 2013). "Mice with deleted CXCL10 gene are partially protected against experimental cerebral malaria (ECM) mortality indicating the importance of CXCL10 in the pathogenesis of CM." (PMID 23630573, 2013). "CXCL10 is also induced in response to cerebral malaria and trypanosome infection." (PMID 40985448, 2025). "Additionally, a field study in Ghana found higher CXCL10 levels from postmortem cerebral spinal fluid (CSF) in cerebral malaria patients." (PMID 37465667, 2023). "In the early stage after the onset of neurological symptoms (day 12 post infection), curcumin, AE (650 μg) and AC-treated animals showed inhibition of P. berghei 18S rRNA, CXCL10 and TNFα mRNAs, similar to the results obtained when curcumin was given before the onset of cerebral malaria symptoms." (PMID 26227888, 2015). "A role for CXCL10 in the pathogenesis of cerebral malaria has also been described." (PMID 24890566, 2014).
cerebral malaria (continued). "The CXCR3 ligands CXCL9 and CXCL10 are also required for the development of cerebral malaria, but they are expressed in a tissue dependent manner with microglia having increased levels of CXCL9 and astrocytes having increased levels of CXCL10, while the levels of both were elevated in neurons." (PMID 24472559, 2014). "Combined genotype frequencies of CXCL10 polymorphisms in patients with cerebral malaria and non-cerebral malaria." (PMID 24349056, 2013). "Stratification analysis of combined genotype frequencies of CXCL10 polymorphisms in patients with cerebral malaria and non-cerebral malaria." (PMID 24349056, 2013). "Interestingly, it has recently been demonstrated that pharmacologically reducing or eliminating CXCL10 improved survival of mice with experimental cerebral malaria." (PMID 24349056, 2013). "Additionally, levels of IL-1ra, G-CSF, VEGF, CCL4 and CXCL10 were found modulated in either the CSF or plasma of patients suffering from cerebral malaria, and could potentially be also modulated in HAT patients." (PMID 19554086, 2009). "However, future analysis is necessary to confirm or investigate this hypothesis, mainly by evaluating the production levels of CCL2, CCL4, CXCL4, CXCL8, CXCL10, and the receptors CXCR3 and CCR2, correlated with susceptibility to cerebral malaria and lung inflammation." (PMID 38256880, 2023). "We have previously shown that free heme is a potent apoptotic factor as well as inducer of the pro-inflammatory chemokine CXCL10 in microvasculature (HBVEC) in vitro and in murine models of experimental cerebral malaria (ECM)." (PMID 26555697, 2015). "There is strong evidence that CXCL9 or CXCL10 and their receptor CXCR3 are required for the development of murine cerebral malaria." (PMID 25177551, 2014). "CXCL10 functions as a chemokine and deletion of its receptor, CXCR3, is protective in experimental cerebral malaria." (PMID 23874969, 2013). "We first clarified the roles of Heme/HO-1, CXCL10/CXCR3 and STAT3 in CM pathogenesis utilizing a well established experimental cerebral malaria mouse (ECM, P. berghei ANKA) model." (PMID 22479586, 2012). "The CXCL10 level was also demonstrated to be elevated in patients with cerebral malaria, and pointed out as potentially inducing apoptosis of endothelial cells leading to BBB breakdown Recent work has suggested that neuronal apoptosis associated with calcium dysregulation may be induced by CXCL10." (PMID 19554086, 2009). "The chemokine CXCL10 is present at high levels in fatal cases of cerebral malaria patients, but is reduced in patients who survive and do not have complications." (PMID 34381047, 2021). "Recent studies in our laboratory and others have revealed a hitherto unknown correlation between chemokine CXCL10/CXCR3, Heme/HO-1 and STAT3 and cerebral malaria severity and mortality." (PMID 22479586, 2012). "In mouse models of experimental cerebral malaria (ECM), phagocytosis of parasite-derived vesicles by astrocytes and IEs by brain macrophages (microglia cells) led to increased production of inflammatory mediators such as CXCL-10 and high levels of CXCL-10 predicted mortality in ECM." (PMID 34271941, 2021).
HIV-1 infection (42 papers, 2009 to 2025). The type species of lentivirus and the etiologic agent of acquired immunodeficiency syndrome (AIDS). "It has been reported that plasma CXCL10 levels are associated with rapid disease progression in early HIV-1 infection and increased levels in plasma and small intestine are associated with a more rapid HIV/SIV disease onset after infection." (PMID 35911692, 2022). "A few studies have shown a correlation between elevated levels of CXCL10 in the CSF and plasma of individuals with HIV-1 infection and the association of CXCL10 with the severity of clinical symptoms." (PMID 23078780, 2012). "Macrophage activation and secretion of proinflammatory cytokines and chemokines, such as IP-10 (also known as CXCL10) and type I IFNs, caused by HIV-1 infection may have a significant impact on pathogenesis." (PMID 38400063, 2024). "We identified a cluster of IRPs (cluster 7), including CXCL11, CXCL9, TNF, CXCL10, and IL18, which was closely associated with T cell dysregulation during chronic HIV-1 infection." (PMID 36408648, 2023). "During primary HIV-1 infection, CXCL10 plasma levels predict disease progression even better than plasma viral loads or CD4 +T cell counts." (PMID 30717826, 2019). "Elevated blood CXCL10/IP-10 levels during primary HIV-1 infection (PHI) were described as an independent marker of rapid disease onset, more robust than peak viremia or CD4 cell nadir." (PMID 27509048, 2016). "Already in the acute primary phase of HIV-1 infection, the levels of soluble inflammatory mediators, such as IP-10 (CXCL10), were predictive of disease progression." (PMID 24991927, 2014). "We have demonstrated induction of CXCL10 and other chemokines/cytokines during HIV-1 infection in the brain, as well as synergism of CXCL10 with HIV-1 in neuronal toxicity, which was dampened by bryostatin." (PMID 23078780, 2012). "CXCL10 has been detected in the cerebrospinal fluid of individuals with HIV-1 infection and in the brains of individuals with HIV-associated dementia, but was absent in uninfected control individuals." (PMID 22393386, 2012). "Increased levels of CXCL10 have been detected in the CSF and plasma of individuals with HIV-1 infection." (PMID 19479051, 2009). "Additionally, 15 cytokines and 1 chemokine (CXCL10) are present at higher levels in rapid relative to slow disease progressors during acute HIV-1 infection." (PMID 31836011, 2019). "In the Swiss HIV Cohort, we found that CXCL10, CCL2 and, to a lesser extent, CXCL9 transcripts were significantly upregulated during untreated HIV-1 infection." (PMID 37601355, 2023). "A previous study demonstrated that CXCL9, CXCL10, and CXCL11 levels can predict HIV-1 disease progression during primary HIV-1 infection." (PMID 36408648, 2023). "We have shown that HIV-1 infection in macrophages or treatment of astrocytes with TNF-α and HIV-1 modulates CXCL10 expression, which leads to neuro-toxicity." (PMID 23078780, 2012). "On further in vitro investigation of astrocytes, macrophages, and lymphocytes, we found that CXCL10 was induced by HIV-1 infection or treatment with TNF-α or IFN-γ, suggesting that myeloid and lymphoid cell populations are key players in CXCL10." (PMID 23078780, 2012). "Overall, we conclude not only that CXCL10 is upregulated in HIV-D patients, but that, in combination with HIV-1, can have a profound impact on neuroglial health in the neuro-HIV-1 infection setting." (PMID 23078780, 2012). "One example of this is miR-21 targeting of interferon-γ-induced protein 10 (IP-10 or CXCL-10), a chemokine involved in trafficking immune cells to inflammatory sites, whose plasma levels are up-regulated after HIV-1 infection and positively correlated to disease progression." (PMID 38790203, 2024). "In addition, chronic HIV-1 infection increases SLAMF7 expression, whereas SLAMF7 negatively regulates IFN-α–mediated CXCL10 production to inhibit the induction of inflammatory monocyte subsets." (PMID 36749634, 2023).
HIV-1 infection (continued). "CXCL10 (IFN-γ -inducible protein 10, also known as IP-10), a CXC chemokine, was one of the chemokines found to be significantly elevated during the early stages of HIV-1 infection." (PMID 34527676, 2021). "A panel of plasma CXCL9, CXCL10, and CXCL11 measured during primary HIV-1 infection could predict long-term HIV disease prognosis in an MSM group and has potential as a novel biomarker in the clinic." (PMID 31836011, 2019). "HIV-1 infection elicited proinflammatory response in the immunological milieu of the liver in HIV-infected mice compared to uninfected animals, as determined by upregulation of IL23, CXCL10 and multiple toll-like receptor expression." (PMID 29361613, 2018). "Many studies have previously reported a correlation between the observed increase in the production of pro-inflammatory cytokines IL-1β, IL-6, IL-18 and TNF-α; and IFN inducible chemokines CXCL9, CXCL10 and CXCL11 during the course of HIV-1 infection and the up regulation of HIV-1 replication." (PMID 29373606, 2018). "In addition, IRF7-induced genes important for cell trafficking (e.g., CXCL10 and ITGB7) may promote migration of effector cells to the mucosal sites where HIV-1 infection will occur." (PMID 30787294, 2019). "Irrespective of the lack of productive HIV-1 infection, co-treatment of astrocytes with TNF-α and HIV-1 particles for 48 h showed upregulation of CXCL10 expression." (PMID 23078780, 2012). "Production of IL-12, IL-6, CCL-2, CXCL-10 and CXCL-12, that were also detected at day 14, was not significantly affected by either R5 or X4 HIV-1 infection (data not show)." (PMID 21767373, 2011).